MOSMO (modulator of smoothened)
Description:
Acts as a negative regulator of hedgehog signaling probably by promoting internalization and subsequent degradation of smoothened protein (SMO) present in the ciliary membrane. Plays a role in sonic hedgehog (SHH)-induced spinal neural progenitor cells differentiation.
Synonyms: ATTHOG; C16orf52; BC030336
Tractability: Antibody: UniProt places it where antibodies can reach, with medium confidence; UniProt predicts a signal peptide or a membrane-spanning region; its Gene Ontology location is reachable by antibodies, with medium confidence.
Gene: Protein-coding gene on chromosome 16 (22,007,638 to 22,087,534, forward strand). Ensembl gene ENSG00000185716.
Subcellular location: Cell projection, cilium membrane; Cell membrane
Gene Ontology:
Biological process: negative regulation of smoothened signaling pathway; regulation of neuron differentiation; regulation of protein stability
Cellular component: ciliary membrane; Golgi apparatus; plasma membrane
Genetic constraint (gnomAD): Loss-of-function variants: 5 observed, 11.44 expected, observed/expected ratio (o/e) 0.44, 90% interval 0.23 to 0.92. The upper end of that interval is the gene's LOEUF score, 0.92, which puts it in group 3 of 6, group 1 being the genes least tolerant of losing a copy. Missense variants: 90 observed, 133.98 expected, observed/expected ratio (o/e) 0.67, 90% interval 0.56 to 0.8. Synonymous variants: 59 observed, 55.3 expected, observed/expected ratio (o/e) 1.07, 90% interval 0.86 to 1.33.
Homologues: Orthologues: chimpanzee MOSMO (100% identical), dog MOSMO (100% identical), guinea pig MOSMO (100% identical), mouse Mosmo (100% identical), pig MOSMO (100% identical), rat Mosmo (100% identical), tropical clawed frog mosmo (100% identical), macaque MOSMO (99% identical), rabbit MOSMO (99% identical), zebrafish mosmob (90% identical), Drosophila melanogaster CG14182 (51% identical).
Diseases named in the same sentence as MOSMO in open-access papers:
MOSMO is named in the same sentence as 2 diseases in open-access papers, as found by Europe PMC text mining. Sharing a sentence is not in itself a finding about the gene and the disease.
MOSMO shares sentences with these, for which no sentence is quoted: breast carcinoma (1 paper); deafness (1).